EGFR (epidermal growth factor receptor)
Diseases named in the same sentence as EGFR in open-access papers (continued):
Sharing a sentence is not in itself a finding about the gene and the disease.
cancer (continued). "The glycosylation on the cell surface proteins including EGF receptor (EGFR) has been shown to play a role in cancer biology and cellular proliferation." (PMID 29339807, 2018). "The targeting of EGFR in cancers is quite limited due to the status of the Kirsten rat sarcoma 2 viral oncogene homolog (KRAS) mutation." (PMID 30583572, 2018). "These inhibitors induce apoptosis in cancer cells by blocking multiple EGFR-dependent growth and survival signaling pathways (Chong and Jänne 2013)." (PMID 30134822, 2018). "This possibility is strongly supported by the divergent responses of cancer cells to EGFR TKIs, vs. downregulation of EGFR protein." (PMID 29358623, 2018). "Radionuclide molecular imaging of EGFR expression should enable personalization of anti-cancer treatment." (PMID 29728916, 2018). "Afatinib plus bevacizumab exerts a strong synergistic effect against cancer cells after acquired resistance to EGFR-TKIs." (PMID 30410675, 2018). "Next, we developed an in vitro antibody binding/uptake assay to enable selection of an antibody with optimized affinity such that binding and uptake by EGFR occurs more efficiently on overexpressing cancer cells compared to normal cells." (PMID 30323890, 2018). "The analogous 4-(indole-3-yl)quinazolines were found to be highly potent EGFR-TK inhibitors with excellent cytotoxic properties against several cancer cell lines." (PMID 30065164, 2018). "This is true for targeted therapies using tyrosine kinase inhibitors for EGFR or BRAF mutant cancers, but is also an increasingly recognized problem for immunotherapies." (PMID 29192388, 2018). "In this study, EGFR-positive cancer stem-like cells (CSLCs) derived from HCT116 and HT29 cells were used as study models for in vitro inductions." (PMID 30068339, 2018). "EGFR inhibitors can sensitise cancer cells to radiation both in vitro and in vivo, with positive results also observed in a Phase III trial in head and neck cancer." (PMID 29439394, 2018). "Activation of EGFR, which enables cancer cells to bypass crizotinib-mediated inhibition of ROS1 signalling, has been described as a mechanism of resistance to crizotinib in ROS1-rearranged NSCLC." (PMID 30029601, 2018). "We, for the first time, demonstrate how P.A can function through a combination of AMPK activation and EGFR inhibition, resulting in a potent anti-cancer effect." (PMID 29899551, 2018). "The data presented so far have demonstrated that peptide 327 and TAT-327 effectively inhibited downstream targets of EGFR in cancer cells." (PMID 29515106, 2018). "Based on population-level cancer registry data, guidelines recommend EGFR testing for approximately 75,000 patients." (PMID 29554880, 2018). "Several randomized trials have evaluated the potential clinical activity of the combination of EGFR-targeted agents with chemotherapy in advanced cancers, particularly NSCLC." (PMID 30088048, 2018). "To investigate the antianaplastic cancer activity of afatinib and the essential role of EGFR in SW579 cells in vitro, we determined the IC50 value of afatinib in SW579 cells by treating them with different concentrations of afatinib by MTT assay." (PMID 29849821, 2018). "Cetuximab is a monoclonal antibody that binds to the epidermal growth factor receptor, which is important in the growth of many cancers." (PMID 35541738, 2018). "The epidermal growth factor receptor (EGFR) family of receptor tyrosine kinases plays a major role in proliferative signalling in a variety of cancers." (PMID 29712619, 2018). "The EGFR-mediated suppression of IFNγ/TNFα mediated amplification of the T-cell infiltrate in these cancers bears strong similarities with observations in skin inflammation disorders." (PMID 30192802, 2018). "Oncologists had found that there is a strong correlation between elevated growth factors (VEGF and EGFR signaling) and a reduced survival time in patients with untreated cancer." (PMID 29342116, 2018).
cancer (continued). "Previous studies suggested that EGFR was dysregulated in a variety of human cancers and that EGFR TKIs, including erlotinib at clinically relevant concentrations, induced autophagy in NSCLC cells." (PMID 29875309, 2018). "The result was unexpected because numerous studies in HNSCC and other cancer cell lines generally indicated that co-targeting ErbB3 with EGFR or other pathways, chemotherapy, or radiotherapy, was required to yield a significant benefit from ErbB3 inhibition." (PMID 29305574, 2018). "Patients who are particularly well-suited for therapy with EGFR TKIs are those with EGFR phosphorylation-dependent cancer cell proliferation and metastasis." (PMID 30187356, 2018). "Next, we characterized the affinity and the relative amount of EGFR per cell on various cancer cell lines." (PMID 29464066, 2018). "In the context of cancer, many of these client proteins include well-established oncogenes such as mutant EGFR, EML4-ALK, BRAF and HER2 among others." (PMID 30072489, 2018). "Due to the role of MMP-9 in cancer metastasis, the association between EGFR and MMP-9 is an intriguing target for the investigation of EGFR’s involvement in PCa invasion." (PMID 30134822, 2018). "Although EGFR-TKI is an effective therapeutic agent, a long-term treatment with EGFR-TKI sometimes leads cancer cells into EGFR-TKI-tolerance, by which therapeutic options are probably reduced in cancer patients." (PMID 30075033, 2018). "Potent in vitro cytotoxicity of RN765C, with nanomolar to subnanomolar EC50, was observed on a panel of cancer cell lines expressing moderate to high level of EGFR." (PMID 30323890, 2018). "In further microarray studies of other EGFR and ErbB2-driven cancer cells, a largely overlapping group of genes was consistently noted to be regulated." (PMID 29861842, 2018). "It was suggested that this strategy appears to be promising for treatment of cancer that over-express EGFR." (PMID 29315231, 2018). "In 2013, the relationship between testing status and distance to an NCI cancer center was much stronger for KRAS testing than for EGFR testing." (PMID 29554880, 2018). "The EGFR/ERBB family is a representative target for cancer therapy to which small molecule tyrosine kinase inhibitors (TKIs) and monoclonal antibodies (mAbs) are developed, approved and applied." (PMID 30404198, 2018). "Resistance to antitumor immunity can be promoted by the oncogenic pathways operational in human cancers, including the epidermal growth factor receptor (EGFR) pathway." (PMID 30192802, 2018). "Another possible mechanism for Nox4 inducing cancer progression includes histone modification, transforming growth factor-β and epidermal growth factor receptor (EGFR) pathway and so forth." (PMID 30513726, 2018). "It is unclear how abnormally sustained EGFR signaling during mitosis affects cellular processes, however, it does appear to help mitotic cancer cells resist nocodazole-mediated cell death." (PMID 30544639, 2018). "The EGFR signaling pathway plays a major role in innumerable developmental processes in all animals and its deregulation leads to different types of cancer, as well as many other developmental diseases in humans." (PMID 30142157, 2018). "Epidermal growth factor receptor (EGFR) is over-expressed cell types and plays a key role in cancer progression." (PMID 29560830, 2018). "Antibody therapies targeting the epithelial growth factor receptor (EGFR) are being increasingly applied in cancer therapy." (PMID 30301942, 2018). "This proposition was assumed to examine the binding interactions and binding energies within EGFR active site, expecting it to provide useful insights for designing effective drugs to treat EGFR-related cancers." (PMID 30563058, 2018). "Increased phosphorylation of EGFR is often detected in alectinib-resistant cancer cells, and TGF-α blockade occurs in NSCLC with restored sensitivity to alectinib." (PMID 29844868, 2018).
cancer (continued). "EGFR overexpression is observed in many cancer types, including head and neck, lung, colorectal, breast, pancreatic, kidney, ovary, bladder, and prostate cancers." (PMID 29872734, 2018). "Here we showed active type I interferon signaling in the skin lesions of cancer patients undergoing treatment with the anti-EGFR drug cetuximab." (PMID 30200670, 2018). "These receptors can also induce resistance to EGFR-TKIs, suggesting they are major alternative bypass signaling escape methods from ErbB/Her family receptors in cancer." (PMID 30404198, 2018). "The Epidermal Growth Factor (EGF) and its receptor, the Epidermal Growth Factor Receptor (EGFR), are involved in cancer patients with poor prognosis, of which 80–90% are associated with HNSCCs." (PMID 30308958, 2018). "The EGFR signaling pathway plays important roles in the proliferation, survival, migration, and metastasis of cancer cells." (PMID 29435193, 2018). "Several clinical studies indicate that overexpression of inflammatory cytokines, such as IL-1, IL8, IL6 or CXCL1, correlates with cancer progression and decreased response to EGFR targeting therapy." (PMID 30261609, 2018). "The targeted EGFR agents provide more treatment options and better therapeutic outcomes for the cancer patients whose tumors are driven by mutant EGFRs." (PMID 29642553, 2018). "These antibodies were produced for anti-cancer treatments to prevent EGFR function by binding to the receptor." (PMID 30104638, 2018). "Our results regarding the structure of PGRMC1 clearly showed that the heme-stacking dimerization of PGRMC1 facilitates cancer proliferation and chemoresistance by activating EGFR signaling and detoxification by cytochrome P450." (PMID 30087538, 2018). "Nimotuzumab is a humanized anti-epidermal growth factor receptor (EGFR) monoclonal antibody that is approved in many countries for the treatment of EGFR-positive cancers." (PMID 29464066, 2018). "EGFR has been shown to activate the choline kinase-alpha or phosphatidylcholine-specific phospholipase C in some cancer models." (PMID 29983881, 2018). "In preclinical studies, Gefitinib demonstrated antitumor activity in several human cancer cell lines over-expressing EGFR, including lung, ovarian, breast, and colon cancer cell lines." (PMID 30483135, 2018). "Late-evolving EGFR T790M in cancer cells that acquired resistance showed a decreased apoptotic response to EGFR-TKI." (PMID 30291293, 2018). "In fact, EGFR was reported to be responsible for maintaining the survival of cancer stem-like cells (CSLCs) in EGFR-positive cancers." (PMID 30068339, 2018). "The combination of genistein with gefitinib, a drug widely used in the treatment of various cancers, can inhibit cell proliferation and induce apoptosis in drug resistant H1975 NSCLC cells, which harbor an epidermal growth factor receptor (EGFR) mutation." (PMID 30200668, 2018). "It is reported that more than 80% EGFR mutations in NSCLC are deletions in exon 19 and a point mutation (L858R) in exon 21, which induces the constitutive activation of EGFR in the EGFR mutant cancer cells." (PMID 30425968, 2018). "Although EGFR-TKIs show an excellent therapeutic effect on EGFR-mutated NSCLC, most cancers develop resistance to EGFR-TKI." (PMID 30445769, 2018). "In this context, EGFR signaling has been involved in the regulation of several metabolic processes that are critical for cancer cell proliferation: from the biosynthesis of fatty acids and pyrimidines, to glucose catabolism." (PMID 29124875, 2018). "Based on their overexpression and prosurvival signaling in numerous malignancies, β1 integrin and EGFR are anticipated as potential cancer targets." (PMID 29719593, 2018). "In comparison, three sets of 163 randomly picked genes yielded average 6% cancer genes, 4% EGFR/Ras/MAPK pathway genes, and 0–5% of other CRC pathway genes." (PMID 29301589, 2018).
cancer (continued). "Activating mutations in EGFR renders this RTK constantly active, which in many cases behaves as a cancer driver that governs cancer growth." (PMID 29976202, 2018). "On the other hand, TKIs which are highly selective for EGFR tyrosine kinase can inhibit autophosphorylation in a variety of EGFR-expressing human cancer cell lines." (PMID 30563058, 2018). "We developed a clinical-grade 89Zr-DFO-nimotuzumab as a potential immunoPET agent for imaging of patients with EGFR-positive cancers." (PMID 29682209, 2018). "This clearly emphasizes the urgent need for a more precise control of highly effective EGFR directed cancer treatments." (PMID 29876011, 2018). "Most current findings support the notion that autophagy induced by anti-EGFR mAbs acts as a protective response in cancer cells." (PMID 30427914, 2018). "Overexpression of EGFR is a common phenomenon in TNBC and nuclear EGFR expression correlates with a more aggressive clinical behavior in these cancers." (PMID 29796172, 2018). "HSP90 is a chaperon protein that has been demonstrated to bind and stabilize HER1 and whose inhibition causes a decrease in EGFR in cancer cells." (PMID 29777377, 2018). "EGFR was correlated with cancer progression and poor survival in addition to the development of resistance to cytotoxic agents." (PMID 30515268, 2018). "Epidermal growth factor receptor (EGFR) is also a well-known targeting moiety, which has been well-explored for the targeted drug delivery in cancer cells." (PMID 29881657, 2018). "In turn CAF-derived TGFα induces epidermal growth factor (EGFR) signaling in cancer cells which stimulates cancer cell growth." (PMID 29854318, 2018). "Both EGFR-specific TM preparations were proven to be suitable for cancer immunotherapy and PET-imaging of tumors." (PMID 29876011, 2018). "There is a need for fluorescent imaging probes for these and other EGFR positive cancers that can be used for image-guided surgery." (PMID 29464066, 2018). "Seven out of 57 patients harbored mutations in the exons 18–21 of EGFR, coding for the TKD: of them, two were novel mutations, while the others were already described in literature in other cancer types." (PMID 29352306, 2018). "Other molecular targets, such as HER-2, VEGF and EGFR, have also been associated with PI3K pathways in cancers." (PMID 29408858, 2018). "Here, the insertion of scFvs to three additional cancer targets—EGFR (epidermal growth factor receptor), EGFRvIII, and PSMA (prostate specific membrane antigen)—in gD Δ6–38 enabled the generation of specifically retargeted o-HSVs." (PMID 29966356, 2018). "Another 13 EGFR-mutant patients who received Bev + CP regimen in second- or further-line anti-cancer treatment after failure in first-line EGFR-TKIs were included in our study for comparison." (PMID 28702789, 2018). "Most probably, the charge and polarity environments of these 13 motifs represent optimal environments for N-glycosylation, as the EGFR studied were isolated from proliferating cultured cancer cells." (PMID 29541627, 2018). "Decreased expression of EGFR or AKT has been shown to increase radiation sensitivity in human cancer cells." (PMID 29439394, 2018). "Anti-EGFR antibodies e.g. cetuximab, panitumumab, and nimotuzumab have been used for treating different EGFR-positive cancers." (PMID 29682209, 2018). "This argued with the activation of the EGFR-mediated ubiquitin-degradation pathway shortly after the exposure of cancer cells to NBD compounds." (PMID 29702613, 2018). "EGFR has been primarily linked to adenocarcinoma, where alterations in this gene represent a cancer-driving force, and anti-EGFR therapy is approved for patients with these alterations." (PMID 29731995, 2018). "For example, oncogenic EGFR-KDD and BRAF-KDD have been reported in human cancers, along with their responses to the respective targeted therapies against EGFR and BRAF." (PMID 29455648, 2018).
cancer (continued). "In this study, we found stromal cell-derived SPINK1 not only activates Akt/mTOR, Mek/Erk/Stat3 pathways, signaling branches downstream of EGFR, but also generates profound impact on cancer cell transcriptomics." (PMID 30333494, 2018). "EGFR is able to form a complex with β-catenin, increasing the invasiveness and frequency of metastasis of cancer cells." (PMID 30187356, 2018). "We report a positive clinical outcome for a cancer patient treated with the combination of an anti-EGFR mAb (Nimotuzumab) and anti-NGcGM3 therapy (NGcGM3/VSSP vaccine)." (PMID 29844873, 2018). "There are 36 protein kinases in the Cancer Gene Census; seven of them (EGFR, ERBB2, BRAF, FLT3, PRKACA, LCK, and FGFR2) had enriched PTM/mutation domains in our study." (PMID 29695735, 2018). "For example, cetuximab, used for inhibiting epidermal growth factor receptor (EGFR) on cancer cells, can be recognized by NK cells through CD16 receptors and produce apoptosis." (PMID 30567306, 2018). "EGFR, α7-nAChR, and β-AR each play pivotal roles in regulating the alkaloid-induced growth and progression of cancer cells." (PMID 30148841, 2018). "Most cancers acquire resistance to anti-cancer drugs, including gefitinib, one of the most well-characterized molecular-targeting anti-cancer drugs for EGFR in lung adenocarcinomas, after a period of drug treatment." (PMID 29472726, 2018). "Of the 163 recurrently targeted genes in the two different genetic backgrounds, one-third were known cancer genes and one-fifth had links to the EGFR/Ras/MAPK pathway." (PMID 29301589, 2018). "Through the investigation of cancer therapy outcomes, an important relationship between EGFR and MET signaling was established." (PMID 29926131, 2018). "When the shielded particles are equipped with adaptor proteins, the virions deliver their payload genes into human cancer cells expressing HER2 or EGFR." (PMID 29386504, 2018). "Lastly, we demonstrate that PHLDA2 expression has functional impact in EGFR/ErbB2-driven cancer cells and can modulate the efficacy of molecularly targeted therapy." (PMID 29861842, 2018). "Very recently, it has been reported that disialogangliosides, such as GD3 and GD2, enhance EGFR signaling, resulting in the expression of a cancer stem cell phenotype and a reduced sensitivity to Gefitinib." (PMID 29462882, 2018). "Targeted and combinational therapeutic strategies have been successfully applied for treating EGFR-driven cancers." (PMID 29642553, 2018). "Earlier studies showed that inhibition of COX-2 (by NS-398) along with epidermal growth factor receptor (EGFR) (through gefitinib) resulted in increased cytotoxicity of Docetaxel along with reduced cancer cell migration." (PMID 29719610, 2018). "A role of EGFR in p27 regulation is also underscored by clinical studies reporting elevated cutaneous p27 protein levels in cancer patients under systemic EGFR inhibitor therapy." (PMID 30013037, 2018). "Targeting EGFR using specific TKIs like gefitinib brings back cancer cells sensitivity to RET inhibitors." (PMID 29455670, 2018). "In recent years, therapeutic drugs targeting the epidermal growth factor receptor (EGFR) such as cetuximab and nimotuzumab have been used to treat malignant tumors of the head and neck because of their low adverse effects." (PMID 30414263, 2018). "Higher affinity of scFv to EGFR is required for efficient combination to discriminate the damage activities between EGFR-overexpressed cancer cells and relatively low EGFR-expressed normal cells." (PMID 29415996, 2018). "This limited clinical activity is often due to the existence of compensatory pathways that confer resistance to EGFR inhibition, thus allowing continued cancer cell growth and survival." (PMID 29795369, 2018). "C60 fullerenes use high antioxidant activity and the blocking of specific cell receptors, such as EGFR, to efficiently inhibit the growth of transplanted malignant tumors." (PMID 30347840, 2018).